AGR2 (anterior gradient 2, protein disulphide isomerase family member)
Diseases named in the same sentence as AGR2 in open-access papers (continued):
Sharing a sentence is not in itself a finding about the gene and the disease.
tumor (continued). "Blocking TGF-β was shown to enhance the anti-tumor response of T cells, suggesting that patients displaying AGR2 overexpression might benefit from a combination therapy involving immunosuppressants and TGF-β blockers." (PMID 39062458, 2024). "Along these lines, our previous study demonstrated a significant association between serum AGR2 concentration in CMT-afflicted dogs and distant tumor metastasis, as well as worse overall survival, suggesting the potential utility of serum AGR2 as a prognostic indicator for CMT." (PMID 38822246, 2024). "AGR2 in cancer cells plays a key role in modulating communication between immune cells by orchestrating cytokine–chemokine signaling and immune infiltration, thereby influencing the tumor immune microenvironment." (PMID 39062458, 2024). "These enhanced tumor-killing effects, primarily exploiting AGR2 overexpression in tumor cells, could enhance the efficacy of monoclonal antibody therapy." (PMID 39062458, 2024). "At this juncture, dendritic cells may actually promote tumor growth, with the additional contribution of AGR2 to immune evasion by tumor cells." (PMID 39062458, 2024). "In recent years, there has been increasing evidence suggesting that AGR2 may be involved in tumor development, invasion, and metastasis." (PMID 39062458, 2024). "Knocking down AGR2 expression has shown tumor-suppressive effects." (PMID 39062458, 2024). "This enhancing effect is contingent upon the homodimerization domain of AGR2; thus, monoclonal antibodies targeting AGR2 self-dimerization may emerge as novel therapeutic agents for tumor treatment." (PMID 39281319, 2024). "However, it is important to mention that both TGF-β and TNF-α are actively secreted during the inflammation stage and have been shown to inhibit AGR2 expression in tumor systems." (PMID 37175601, 2023). "Overexpression of intracellular AGR2 may represent an intermediate entity between endoplasmic reticulum and tumor development." (PMID 37197416, 2023). "It has certain reference value to infer whether the patient has a primary tumor and whether the tumor has metastasized based on the expression level of AGR2." (PMID 37197416, 2023). "The combination of proteasome inhibitor and bevacizumab could enhance the anti-tumor efficiency of bevacizumab by decreasing the expression level of AGR2 and reducing its role in tumor cell angiogenesis." (PMID 37197416, 2023). "High AGR2 expression was significantly correlated with high AFP and ALT levels, a high predicted risk metastasis signature score, a large primary tumor size and more advanced pathological stages of HCC." (PMID 36899352, 2023). "Moreover, immunohistochemical staining was utilized to examine the expression of AGR2 in 24 clinical HCC tissues, and the results indicated that AGR2 was highly expressed in tumor tissues compared to normal tissues." (PMID 36899352, 2023). "Two tumor suppressors involved in epigenetic regulation were progressively lost in LGSC and its corresponding metastasis (ZMYND10, OSCP1/NOR1), as was Anterior Gradient Protein 2/3 (AGR2/3) previously implicated in the progression of SBT to LGSC16." (PMID 38014221, 2023). "Moreover, extracellular AGR2 has been shown to bind directly to VEGF to enhance tumor angiogenesis and other activities." (PMID 36899352, 2023). "AGR2 in the extracellular environment may have a critical impact on the homeostasis of the tumor niche, which is a microenvironment conducive to tumor growth." (PMID 37197416, 2023). "For example, by constructing the bispecific antibodies of AGR2 antibody and immune checkpoint proteins, it can play its role in tumor tissue with maximum target concentration, which is a clinical transformation direction to improve the efficacy and reduce side effects." (PMID 37197416, 2023). "Surprisingly, AGR2 was detected in the nucleus in both cell lines, a unique feature that was not seen in situ, suggesting that AGR2 behaviour is likely to be responsive to the tumour microenvironment." (PMID 36482387, 2022).
tumor (continued). "Overexpressed in ER+ BC cells, AGR2 may also promote BCLuM via the (de)regulation of tumor cell adhesion and spread." (PMID 35804819, 2022). "Thus, AGR2 is related to the proliferation, metastasis, invasion, and drug resistance of tumor cells, making it an attractive target for early diagnosis and tumor therapy." (PMID 35719915, 2022). "Therefore, further studies discussing the mechanism of secreted AGR2 in tumor growth and metastasis are necessary." (PMID 33413231, 2021). "Anterior gradient 2 (AGR2) encodes an endoplasmic reticulum (ER)-resident protein that belongs to the protein disulfide isomerase family and is usually secreted into the extracellular matrix (ECM) and plays a pivotal role in tumor microenvironment development." (PMID 34925322, 2021). "Hence, AGR2 can stimulate tumour growth, invasion, resistance to chemotherapy and metastasis, in a wide range of human adenocarcinoma types." (PMID 34452625, 2021). "The aim of this study to explore SOX2 and AGR2 biomarkers expression in tumor tissue of ER-positive breast cancer patients in combination with estimation of serum AGR2 level of these patients in order to validate these biomarkers in the early prediction of tamoxifen resistance." (PMID 34567804, 2021). "The multivariate Cox regression analysis including patient age, FIGO stage, and residual tumour after surgery showed that high AGR2 expression was an independent prognostic marker, both for OS (hazard ratio (HR) = 2.60, p = 0.023) and PFS (HR = 3.89, p = 0.001)." (PMID 34452625, 2021). "The aim of this work is to explore SOX2 and AGR2 biomarker expression in the tumor tissue of ER-positive breast cancer patients in combination with the evaluation of serum AGR2 level of these patients in order to validate these biomarkers as early predictors of tamoxifen resistance." (PMID 34567804, 2021). "The aim of this study is to explore SOX2 and AGR2 biomarkers expression in tumor tissue of ER-positive breast cancer patients in combination with evaluation of serum AGR2 level of these patients in order to validate these biomarkers as early predictors of tamoxifen resistance." (PMID 34567804, 2021). "Additionally, aberrant localization of AGR2 at the tumor cell surface in MMT tissues was noted in some cases." (PMID 34679944, 2021). "However, AGR2 expression is lost when tumour cells were re-isolated from the xenografted tumours and re-cultured in vitro." (PMID 34452625, 2021). "Of note were GDF15 and AGR2, which are purportedly involved in tumour progression." (PMID 33000006, 2020). "While these findings support the functional role of AGR2 as a positive regulator of tumor growth, they also show that AGR2 depletion may promote the escape of tumor cells from the site of injection and their spread to the lungs." (PMID 32570918, 2020). "An increase in AGR2 levels has been reported in a variety of tumor tissues, but the molecular events resulting in the elevated AGR2 in tumor cells, as well as the clinical outcomes of AGR2 upregulation in tumors, remain largely unknown." (PMID 32322663, 2020). "Hypoxic regulation of AGR2 in tumor biology has been previously documented." (PMID 32322663, 2020). "In addition, AGR2 appears to be one of the key players in forming the tumor niche and remodeling the tumor microenvironment to promote malignant growth with metastasis spread." (PMID 32268506, 2020). "Taken together, these data indicate that the expression of AGR2 may be attenuated in tumor cells directly by binding ZEB1 to the AGR2 promoter or indirectly by inhibition of miR-200c transcription." (PMID 32570918, 2020).
tumor (continued). "Indeed, we found that inhibition of ZEB1 counteracted the effects of AGR2 knockout on the invasiveness of tumor cells, as shown by the invasion assay." (PMID 32570918, 2020). "Finally, the in vivo experiments further verified the anti-tumor effects of LINC00460 / miR-342-3p / AGR2 axis in HCC." (PMID 32493835, 2020). "Intracellular AGR2 overexpression could represent an intermediary entity between the ER and tumour development." (PMID 33005802, 2020). "As such, these nanoconjugates might be used to normalize tumor vessels using AGR2 as an anti-angiogenic tumor target." (PMID 31475143, 2019). "An important novel finding in our study was the activation of AGR2 in OPA tumor cells." (PMID 31434729, 2019). "Interestingly, the induction of the AGR2 protein in the PDAC tumor cells regulated the expression of several ER chaperones (PDI, CALU and RCN1)." (PMID 31247903, 2019). "The detected AGR2 level was affected by the AuNP treatment in tumor tissues and plasma." (PMID 31247903, 2019). "Further understanding of this phenomenon might lead to AGR2 targeted antibody-based anti-tumour therapy." (PMID 31710263, 2019). "Furthermore, humanized antibodies selected to block the AGR2 protein were shown to effectively inhibit tumor growth in a xenograft model." (PMID 31247903, 2019). "This protein has been detected to be highly expressed in different tumor types, thus giving rise to the hypothesis that AGR2 acts as an oncogene due to its important role in the activation of survival and metastasis pathways." (PMID 31370342, 2019). "Tissue microarray immunohistochemical staining indicated that a low percentage of positive tumour cells for AGR2 (HR (95% CI) = 0.61 (0.43-0.93)), and a low percentage of positive tumour cells for LOX5 expression (HR (95% CI) = 2.53 (1.23-5.22)) are predictors of BCR after RP." (PMID 30559929, 2018). "The involvement of AGR2 in protein folding and endoplasmic reticulum-assisted degradation may, therefore, allow tumour cells to avoid cell death." (PMID 30140383, 2018). "Importantly, a humanized murine antibody targeting AGR2 exhibited inhibition of xenograft tumor growth, confirming the therapeutic utility of anti-AGR2 compounds." (PMID 29937991, 2018). "The role of extracellular AGR2 (eAGR2) is particularly interesting because it enhances tumor angiogenesis and the invasion of vascular endothelial cells and fibroblasts by interaction with vascular endothelial growth factor (VEGF) and fibroblast growth factor 2 (FGF2)." (PMID 29937991, 2018). "Together with the analysis of pre-neoplastic lesions, we speculate that analysis of AGR2 staining, specifically in epithelial cells of the tumor, could be of value in stratifying human PDAC." (PMID 29069604, 2017). "In these studies, quantitative reverse transcription polymerase chain reaction (qRT-PCR) (n = 2) or immunohistochemistry (IHC) staining (n = 16) was used to detect AGR2 expression in tumour tissue, while ELISA (n = 1) or qRT-PCR (n = 1) was employed to measure AGR2 expression in serum samples." (PMID 29138453, 2017). "AGR2 (anterior gradient protein 2) showed the highest difference in mRNA level, being upregulated approximately 800-fold in duct-derived compared with acinar-derived tumor organoids." (PMID 29069604, 2017). "Finally, using orthotopic xenografts we demonstrated that inhibition of either FOXM1 or AGR2 in human PIMAs inhibited mucinous characteristics, and reduced tumor growth and invasion." (PMID 29267283, 2017). "Thus, in Kras-induced tumourigenesis in mice, Agr2 induction is also an early event that precedes visible neoplasia." (PMID 27941872, 2017). "Thus, knockdown of FOXM1 or AGR2 reduced tumor invasion and inhibited mucinous phenotype of human lung A549 adenocarcinomas in vivo." (PMID 29267283, 2017).
tumor (continued). "In the presence of tumor-secreted AGR2, the stromal cells were found to undergo programmed cell death (PCD) characterized by formation of cellular blebs, cell shrinkage, and DNA fragmentation as seen when the stromal cells were UV irradiated or treated by a pro-apoptotic drug." (PMID 27283903, 2016). "Next, to test if the distribution of AGR2 could modify other components of the secretory pathway, a ratiometric comparison of both BiP and CANX was performed in tumor organoids (Sh-ctl) as compared to tumor organoids silenced for AGR2 (Sh-AGR2)." (PMID 27240165, 2016). "To further correlate the amount of AGR2 produced by tumor organoids to the capacity of cancer cells to secrete eAGR2, we transiently blocked protein synthesis using a cycloheximide (CHX) pulse-chase approach and evaluated the amounts of iAGR2 and eAGR2 in tumor organoids." (PMID 27240165, 2016). "Moreover, the addition of eAGR2 to the ECM of AGR2-depleted organoids restored the formation of tumor organoids." (PMID 27240165, 2016). "Due to its ubiquity, tumor secretion of AGR2 must serve an important role in cancer, yet its molecular function is largely unknown." (PMID 27283903, 2016). "Indeed, AGR2 depletion in cancer cells significantly decreased tumor cell proliferation, suggesting that high levels AGR2 in tumor cells is important for sustaining tumor cell growth." (PMID 27240165, 2016). "Moreover, the expression pattern of AGR2 in tumor and non-tumor bronchial organoids was similar to that observed in 2D culture." (PMID 27240165, 2016). "Given that eAGR2 is secreted by tumor organoids and that AGR2 has been reported in the serum of cancer patients with an average level of eAGR2 ranging from 0.5 to 20 ng/ml, we assessed whether eAGR2 might exhibit specific extracellular functions." (PMID 27240165, 2016). "AGR2 silencing dramatically decreased the formation of tumor organoids." (PMID 27240165, 2016). "Interestingly, AGR2 and AGR3 have both been shown to interact with the protein C4.4A (LYPD3), a factor implicated in tumour progression." (PMID 25875093, 2015). "However, the full spectrum of factors and mechanisms regulating AGR2 levels in tumor cells are still poorly understood." (PMID 25956506, 2015). "Therefore, depending on the precise interaction in particular cell types AGR2 can have different effects on tumor cell behavior." (PMID 26445321, 2015). "Since AKT inhibitor and ERK1/2 inhibitor also abolish the IGF-1 signaling, for anti-ER drug-resistant tumor with an elevated AGR2 level, our study also indicated that targeting IGF-1/AGR2 pathway might be a treatment strategy." (PMID 25956506, 2015). "Additionally, we have included splice transcripts of AGR2 in our study as they are more abundant in tumor tissue for providing growth and survival advantages." (PMID 25237833, 2014). "Therefore, we used the SNU-478 cells to investigate the tumor promoting role of AGR2 by silencing its expression with an AGR2 shRNA." (PMID 25367337, 2014). "An immunohistochemical analysis of AGR2 expression pattern demonstrated that AGR2 expression in the biliary tract is not tumor specific, but is associated with anatomical location and mucin-secreting phenotype." (PMID 25367337, 2014). "Finally, we examined the effect of AGR2 expression on in vivo tumor formation by injecting an equal number of SNU-478:VEC and SNU-478:KD2 cells into BALB/c-Slc-nu/nu immunocompromised mice." (PMID 25367337, 2014). "Tumor promoting role of AGR2 in vitro and in vivo has been demonstrated in various contexts." (PMID 25367337, 2014).
tumor (continued). "Finally, we showed, for the first time, a novel predictive value for AGR2 expression with regard to tumor recurrence in individuals with higher stage disease." (PMID 21144054, 2010). "Interestingly, in various models of tumor progression, increased AGR2 promotes cell migration, invasion, and presumably metastatic spread." (PMID 21144054, 2010). "Furthermore, AGR2 has been shown to increase tumor cell migration in vitro and the incidence of metastatic lesions in vivo." (PMID 21144054, 2010). "Nonetheless, we observed strong correlations between ER and many genes that have previously been shown to be strongly associated with ER positivity, including GATA3, FOXA1, AGR2, AR, and STC2, in microarray profiling studies of mixed ER-positive and ER-negative tumours." (PMID 17555561, 2007). "Thus, there appears to be a ‘dose response’ relationship between the % cell staining for AGR2 and adverse impact on patient outcome in the ERα-positive group of tumours." (PMID 16598187, 2006). "This indicates that mRNA production is probably the primary control point for expression of AGR2 and is consistent with the mRNA-based subtractive hybridisation approach used to first identify AGR2 as a potential marker of aggressive ERα-positive tumours." (PMID 16598187, 2006). "Thus, the percentage of carcinoma cells stained immunocytochemically in the primary tumours was a reasonable reflection of the level of expression of AGR2 mRNA and protein." (PMID 16598187, 2006). "However, MCF-7 cells when exposed to high levels of oestrogens which induce increased levels of AGR2 assume a more aggressive phenotype in vitro and can form tumours and metastases in nu nu mice in vivo." (PMID 16598187, 2006). "Biologically, the prominence of anti-AGR2 suggests that immune recognition of AGR2-expressing tumor cells reflects ER stress-related neoantigen exposure, whereas anti-TYMS responses may correspond to proliferative or DNA repair-linked antigenicity characteristic of early neoplastic transformation." (PMID 41562247, 2026). "In most cancers derived from tissues with high AGR2 expression in normal cells, such as the colorectum, the breast, the endometrium, and the urothelium, a reduced expression paralleled morphological parameters of tumor aggressiveness such as high histologic grade and advanced stage." (PMID 39533806, 2024). "The reasons for the role of AGR2 loss in tumor progression are not clear." (PMID 39533806, 2024). "MAPK/ERK signaling pathway may also be involved in the role of AGR2 in tumor." (PMID 37197416, 2023). "Meanwhile, AGR2 can be internalized into fibroblasts and cancer cells through endocytosis, then it will interact with β-catenin, resulting in β-catenin accumulation in the nucleus and regulating fibroblasts around tumor cells to affect tumor microenvironment (TME)." (PMID 37197416, 2023). "In vivo, xenografts with AGR2-KD performed elevated tumor suppression compared to PC3-NC in response to crizotinib without showing signs of severe toxicity, suggesting that AGR2 loss exacerbated crizotinib-induced inhibition and may serve as a biomarker for crizotinib responses in vivo." (PMID 37121942, 2023). "AGR2 may promote tumor metastasis through receptor adhesion and functional regulation." (PMID 37197416, 2023). "Thus, although inhibiting AGR2 exon 2B may be therapeutically effective, a preselection of sensitive tumours is likely to be necessary." (PMID 36482387, 2022). "Thus, AGR2 expression is variable, depending on tissue and on tumour type." (PMID 34452625, 2021).